PECAM1 (platelet and endothelial cell adhesion molecule 1)
Diseases named in the same sentence as PECAM1 in open-access papers (continued):
Sharing a sentence is not in itself a finding about the gene and the disease.
lung carcinoma (53 papers, 2002 to 2025). "Our findings revealed that PECAM1 is significantly down-regulated in lung cancer and positively associated with first-progression survival (FPS) among patients." (PMID 40361912, 2025). "Lower PECAM1 expression was positively associated with better first-progression survival (FPS) in lung cancer patients." (PMID 40361912, 2025). "Future studies investigating anti-PECAM-1 IONPs using a lung cancer brain metastasis model in vivo should provide evidence about how anti-PECAM-1 IONPs associate with the blood tumor barrier and metastatic brain tumor." (PMID 24278373, 2013). "Together, our research highlights the multifaceted role of PECAM1 in lung cancer and supports its potential clinical utility." (PMID 40361912, 2025). "Contrary to its association with cancer progression, our research reveals the diminished expression of PECAM1 in lung cancer tissues." (PMID 40361912, 2025). "PECAM1 stands out as a gene with significant prognostic value, warranting further investigation as a potential biomarker and therapeutic target in lung cancer." (PMID 40361912, 2025). "In vivo, 2′-O-methyl-modified siRNACD31 carried by RNAi-mate was successfully delivered, targeting the PECAM-1 gene in the vasculature of nude mouse lung carcinoma xenografts." (PMID 24959215, 2014). "Although PECAM-1 activity on the modulation of endothelial cells and its effects in tumor angiogenesis are known, the effects of targeted delivery of PECAM-1 on the growth of lung cancer requires further investigation." (PMID 24959215, 2014). "Meanwhile, anti-PECAM-1 IONPs demonstrated increased lung accumulation, which provides the potential to simultaneously target lung and lung cancer derived-brain metastasis." (PMID 24278373, 2013). "Recently, PECAM-1 expression has been found on many tumor cells, such as human brain gliomas, carcinoma of the cervix, lung cancer, and breast cancer." (PMID 20074345, 2010). "Integrating such emerging evidence broadens the molecular landscape of lung cancer progression and reinforces the need to evaluate distinct gene signatures—including PECAM1 and ZNF334—across different histological contexts to optimize biomarker-guided strategies for early detection and treatment." (PMID 40361912, 2025). "Further investigation using the Kaplan–Meier plotter revealed that the high expression levels of two hub genes, FOSB and PECAM1, were associated with a significantly extended first-progression survival (FPS) in lung cancer patients, with hazard ratios (HRs) of 0.63 and 0.56, respectively." (PMID 40361912, 2025). "Additionally, PECAM1 phosphorylation contributes to the anoikis resistance of lung cancer cell lines." (PMID 40361912, 2025). "Intriguingly, higher levels of PECAM1 correlate with extended survival among lung cancer patients." (PMID 40361912, 2025). "To obtain a more comprehensive understanding of the expression of AFAP1L1 in lung cancer endothelial cells, we assessed the expression density of well-known endothelial cell marker genes (PECAM1), tip cell marker genes (DLL4 and CXCR4) and AFAP1L1 in the t-SNE projection." (PMID 37737201, 2023). "In addition, we conducted immunohistochemical analysis on the protein expression of PECAM-1 in lung cancer tissues and analyzed the survival of patients with LC with different PECAM-1 expressions." (PMID 33828969, 2021). "Furthermore, we analyzed the correlation of the expression of hub gene in lung cancer tissues, of which PECAM1, VWF, CD34, COL1A1, MMP9 and TIMP1 are closely related." (PMID 33850663, 2021). "Similarly, in postoperative patients with lung cancer, we found that the overall survival of the PECAM-1 high-expression group shows a better trend than the PECAM-1 low-expression group (p = 0.172)." (PMID 33828969, 2021).
lung carcinoma (continued). "On the basis of the previous discussions regarding siRNA delivery systems, the present study possibly provides an important target strategy involving 2′-O-methyl-modified siRNA targeting PECAM-1 using cationic lipids RNAi-mate against the proliferation of lung carcinoma cells." (PMID 24959215, 2014). "The relationship between lung-cancer PECAM-1 expression and cell adhesion, proliferation, and migration prompted speculation that this protein may play a role in the formation of tumor cell aggregates." (PMID 20074345, 2010). "Subtype-specific analysis further confirmed the consistent pattern of PECAM1 expression across magnoid, squamous, and bronchial tumor subtypes compared to normal tissues, indicating the potential of PECAM1 as a target gene for lung cancer with prognostic implications." (PMID 40361912, 2025). "Conversely, seven of the downregulated hub genes (TLR4, PECAM1, SELP, CXCL12, VWF, KDR, and CD34) showed both low expression and good prognosis in lung cancer patients (p < 0.05)." (PMID 33627711, 2021). "Our investigation into the role of PECAM1 in lung cancer through TIMER2.0 analysis revealed a significant negative correlation with tumor purity (Rho = −0.427)." (PMID 40361912, 2025). "The growth of the lung carcinoma xenografts was inhibited by the 2′-O-methyl-modified siRNACD31 and RNAi-mate complexes, and the expression of the PECAM-1 protein was downregulated, with a simultaneous decrease in vascular endothelial growth factor (VEGF) protein in the lung carcinoma xenografts." (PMID 24959215, 2014). "PECAM-1 could be used as a potential therapeutic target on the TME with respect to its activity in the pathogenesis of tumors, including lung cancer." (PMID 24959215, 2014).
glioblastoma (52 papers, 2012 to 2025). The most malignant astrocytic tumor (WHO grade IV). "Our analysis of The Cancer Genome Atlas (TCGA) glioblastoma dataset revealed a positive correlation of REIC/Dkk3 and PDGFB or PECAM1 (CD31), suggesting the role of REIC/Dkk3 in angiogenesis." (PMID 36006934, 2022). "More interestingly, we observed human PECAM1/CD31 and ENG/CD105 expression in all tumor types, with higher rate in glioblastoma and renal cancer xenografts." (PMID 24625025, 2014). "Significant differences between glioblastoma samples and healthy controls were observed for angiopoietin, follistatin, HGF, IL-8, PDGF-BB, PECAM-1 and leptin, with specificity ranging from 59–81% and sensitivity from 40–88%, while infrared-spectroscopy reached 100% sensitivity and 87.5% specificity." (PMID 33316976, 2020). "Because ISH staining for the prototypical endothelial marker CD31 (PECAM1) is not available in the Ivy GAP, analysis of glioblastoma vasculature considered ESM1, MECOM, and ENPEP; genes known to be enriched in endothelial cells." (PMID 39724753, 2024).
breast tumors (47 papers, 1998 to 2025). "To address insufficient blood supply as a possible cause of cell death in MMTV-Cre/Ctsl−/− breast tumors we tested their vascularization by detecting the endothelial marker PECAM1/CD31 by immunohistochemistry (IHC)." (PMID 32707827, 2020). "In breast tumors, expression of plateletendothelial cell adhesion molecule (PECAM-1) and vascular endothelial growthfactor (VEGF) was reduced by TVSE treatment." (PMID 33152052, 2020). "In xenograft breast tumors, MTF treatment of mice resulted in decreased levels of platelet and endothelial cell adhesion molecule 1 (PECAM1; alias, CD31) which was used as an endothelial cell marker to examine changes of vascular branches." (PMID 30241339, 2018).
colon carcinoma (47 papers, 2009 to 2025). "Cellularity and vessel density of the colon tumours were determined at different times by histological analyses using PECAM-1 and haematoxylin to stain the tumour cells." (PMID 23936648, 2013). "PECAM-1 (CD31) is a tumor neovascularization marker and α-SMA is a vascular smooth muscle cell marker in mouse colon cancer tissues." (PMID 39735667, 2025). "Furthermore, EndMT, PECAM-1 and Akt/GSK-3β/β-catenin signaling were analyzed under high glucose (HG) and human colon cancer cell (HCCC) supernatant (SN) or coculture conditions by western and immunofluorescence tests." (PMID 37580771, 2023). "We previously found that the mesenchymal cell marker vimentin was strongly expressed, accompanied by a serious disappearance of PECAM-1, in the endothelium in human colon cancer with DM, comparing to that in CC without DM, which implies high-frequency EndMT events in CC with DM." (PMID 37580771, 2023).
ischemia (42 papers, 2008 to 2024). A hypoperfusion of the BLOOD through an organ or tissue caused by a PATHOLOGIC CONSTRICTION or obstruction of its BLOOD VESSELS, or an absence of BLOOD CIRCULATION. "Under pathological conditions, early and transient increases in PECAM-1 may be associated with the response to stimuli such as ischemia and inflammation." (PMID 30258402, 2018). "In tissue harvested 24 hours after reperfusion, significant changes in gene expression were seen as early as after 1 hour of ischemia: PECAM-1 (3x), MUC1 (6x), and TNF-α (3x)." (PMID 31923917, 2020). "To determine the role of VN in ischemia-induced angiogenesis, we measured capillary density by staining ischemic tissue with anti-PECAM-1 antibody." (PMID 22606350, 2012). "The present findings suggest that the increases in expression of MK, NGF and PECAM-1 induced by treadmill exercise after ischaemia are strongly related to such neuroprotective effects." (PMID 20726846, 2011). "Furthermore, the structure of the blood vessels was assessed in the soleus muscle after 14 days of ischemia by immunohistochemistry of Pecam1." (PMID 31897911, 2020). "Additionally, blocking PECAM-1 attenuated neutrophil migration and accumulation in rat muscle flaps, demonstrating an overall protective effect against ischemia-reperfusion injury." (PMID 31923917, 2020). "The present study revealed that the gene expression of Pecam1 was non-significantly decreased at 4 h, but significantly increased in the neocortex affected by 24 h of ischemia." (PMID 31089963, 2019). "Similar staining patterns of Nefl, Aif1, and Pecam1 were observed in the ischemia-affected striatum (data not shown)." (PMID 31089963, 2019).
colorectal cancer (39 papers, 1995 to 2025). A primary or metastatic malignant neoplasm that affects the colon or rectum. "Sections of colorectal cancer and healthy colon were stained for PECAM-1 (a marker of endothelium) and GRIN2D by IHC." (PMID 26943033, 2016). "Additionally, ST3GAL6-AS1 was co-expressed with a variety of mRNAs, including PECAM1, VCAM1, CXCL12, CD34, CDH5, and VWF, and was associated with colorectal cancer progression." (PMID 33790949, 2021). "This analysis determined that the vessels in colorectal cancer stain strongly for GRIN2D, however, vessels in the healthy colon, marked by PECAM-1 staining do not stain for GRIN2D." (PMID 26943033, 2016).
ovarian carcinoma (37 papers, 2006 to 2024). A malignant neoplasm originating from the surface ovarian epithelium. "Immunohistochemistry on tissue microarray showed that GRB7 and platelet endothelial cell adhesion molecule-1 (PECAM-1/CD31) protein expression were positively correlated in ovarian cancer tissues." (PMID 34783299, 2021). "The co-localization of regulator of G-protein signaling 5 (RGS5), a signal transduction molecule upregulated in endothelial cells in the TME, with PECAM-1 and PDGF receptor (PDGFR)-β, has been reported in various types of cancer, including ovarian cancer." (PMID 36831623, 2023). "The co-localization of GPIIb (CD41), platelet endothelial cell adhesion molecule-1 (PECAM-1; also known as CD31), and VEGF in ovarian cancer tissues suggests the involvement of platelets in angiogenesis and tumor growth." (PMID 36831623, 2023).
vascular tumors (36 papers, 2011 to 2026). "Cluster of differentiation 31 (CD31; also known as platelet endothelial cell adhesion molecule 1 or PECAM-1) is expressed in certain tumors, including epithelioid sarcoma-like hemangioendothelioma, other vascular tumors, histiocytic malignancies, and plasmacytomas." (PMID 24666969, 2014).
gastric cancer (35 papers, 2013 to 2025). A primary or metastatic malignant neoplasm involving the stomach. "A series of studies identified that PECAM1 was linked to development of several malignances and had the potential to be a diagnostic and prognostic biomarker in gastric cancer patients." (PMID 37056778, 2023). "PECAM1 overexpression has been linked to peritoneal recurrence of stage II/III gastric cancer patients." (PMID 31277598, 2019). "In patients with stage II/III gastric cancer, TOP2A, GGH, and PECAM1 levels in primary tumors are linked to high risk of hematogenous, lymph node, and peritoneal recurrence, respectively." (PMID 28915696, 2017). "PECAM1 mRNA levels were higher in diffuse-type than in intestinal-type gastric cancer, whereas the opposite was true for TOP2A and GGH expression (P < 0.0001)." (PMID 28915696, 2017). "Survival analysis revealed that high expression of ST2, PECAM1, CD34, and KRT17 predicted poor prognosis in patients with gastric cancer." (PMID 40860436, 2025). "The data revealed that the expression of ALKBH1 was consistently higher than the other two gastric cancer biomarkers, AQP1 and PECAM1, across all 10 clusters." (PMID 38317214, 2024). "C11_VWF were characterized by co‐expressing marker genes of fibroblasts (COL1A1, FAP, VIM, ACTA2) and endothelial cells (VWF, PECAM1, CLDN5, FLT1, RAMP2), which resembled a subgroup of cells undergoing an EMT transition in gastric cancer." (PMID 38115703, 2023). "In the bulk gastric cancer tissue microarray data, CD34 shows a high correlation with other vascular markers, ESM 1 and PECAM1." (PMID 32293340, 2020).
ischemic stroke (33 papers, 2016 to 2026). A stroke disorder caused by obstruction of blood flow to the brain, due to thrombotic (local blood clot formation) or embolic (due to a blood clot or other material traveling from another site) event. "A clinical study showed that administering clopidogrel with ASA reduced the expression of platelet PECAM-1 in patients who had suffered an ischemic stroke." (PMID 34502520, 2021). "Interestingly, we found that PDGF-D mRNA transcripts (puncta) were potently induced (~ 2-fold) in endothelial cells expressing PECAM1 mRNA transcripts at the lesion site 24 h after ischemic stroke." (PMID 38769116, 2024). "A study of ischemic stroke also suggests that Pecam1 may be involved in the extent of early ischemic brain injury mediated by inflammatory responses." (PMID 37065920, 2023). "MMP-2 has been reported to regulate TJPs, basement membrane proteins, and PECAM-1 as substrates and is involved in BBB breakdown via disruption of TJPs in several neurological diseases such as epilepsy and ischemic stroke." (PMID 37889501, 2023). "Transendothelial migration of PMN is mediated by adhesion molecules, e.g., of intercellular adhesion molecule 1 (ICAM-1) and platelet endothelial cell adhesion molecule-1 (PECAM-1), which exhibit an increased expression after induction of experimental ischemic stroke." (PMID 35087539, 2021).
myocardial infarction (33 papers, 2009 to 2025). Gross necrosis of the myocardium, as a result of interruption of the blood supply to the area, as in coronary thrombosis. "We found that the carriers of allele A (563Asn; G1688A; Ser563Asn) of the same adhesion molecules (PECAM1) also had a higher risk of myocardial infarction if they had a first-degree relative." (PMID 23274712, 2013). "The correlation of these polymorphisms of PECAM1 with coronary artery disease or myocardial infarction was confirmed by other researchers in Japanese and South Indian populations." (PMID 23274712, 2013). "The multivariate analysis shows that the risk of myocardial infarction among carriers of variant G (125 Val) of the polymorphism (C373G; Leu125Val) PECAM1 was almost 1.6-fold that of CC homozygotes (OR 1.571, 95% CI: 1.185–2.082)." (PMID 23274712, 2013). "In conclusion, this study demonstrated that TCM SG dose-dependently improved cardiac hemodynamic function, reduced myocardial infarction size, and promoted myocardium angiogenesis in myocardial infarction rats by upregulating PECAM-1/CD31 and VEGF expression." (PMID 28757887, 2017). "Our study indicates that PECAM1 polymorphisms and the –1562 C/T MMP9 polymorphism have a positive effect on (i.e., increase) the risk of myocardial infarction in subjects under 45 years of age." (PMID 23274712, 2013). "Of the chosen polymorphisms, two (Leu125Val PECAM1 and A1/A2 FVII) are related to myocardial infarction and two (C677T MTHFR and 5A/6A MMP3) to advanced stenosis in arterial vessels (> 75%)." (PMID 23274712, 2013). "Immunofluorescence showed that VCAM-1 was not expressed under basal conditions but was upregulated and clearly localised to glomeruli in mice with myocardial infarction and to the same cells expressing PECAM-1, indicating upregulation by glomerular endothelial cells." (PMID 23471223, 2013). "The association of platelet endothelial cell adhesion molecule 1 (PECAM1), hypoxia-inducible factor 1 subunit alpha (HIF1A), and KIAA1462 in myocardial infarction (MI) was investigated." (PMID 30678728, 2019). "Additionally, the serum levels of platelet endothelial cell adhesion molecule 1 (PECAM-1), which rises following myocardial infarctions and thrombotic events, were also significantly lower at 440 days (p = 0.009)." (PMID 36982525, 2023).
hepatocellular carcinoma (31 papers, 2010 to 2025). A malignant tumor that arises from hepatocytes. "Key markers, such as PTPRC, CD3E, CD4, CD79A, and CD3G in immune cells, EPCAM and KRT19 in epithelial cells, and MME and PECAM1 in stromal cells, were identified, providing crucial insights into hepatocellular carcinoma progression and immune response mechanisms." (PMID 39388011, 2024).